MED12 (mediator complex subunit 12)
Diseases named in the same sentence as MED12 in open-access papers (continued):
Sharing a sentence is not in itself a finding about the gene and the disease.
leiomyoma (continued). "The presence of MED12 variants in nearly 70% of leiomyomas suggests that MED12 plays an important role in the genesis of these tumors in both white and black American women." (PMID 22428002, 2012). "MED12 (Mediator complex subunit 12; Xq13.1) was the only gene that presented with damaging variants in more than one leiomyoma." (PMID 22428002, 2012). "In this study, a set of 28 uterine leiomyomas from 18 South African patients was sequenced for MED12 exon 2 mutations to study the role of MED12 in tumorigenesis of fibroids also in other populations than Finns." (PMID 22182697, 2011). "Recent studies have shown that MED12 mutations, the most common leiomyoma alterations, are associated with tumor characteristics such as tumor size and number of tumors, as well as with treatment response to gonadotropin-releasing hormone agonists and ulipristal acetate." (PMID 41162745, 2025). "MED12 mutations have been identified in uterine fibroids among women from diverse ethnic backgrounds—including North American, European, African, Asian, and Middle Eastern populations—highlighting its role as a major driver in leiomyoma pathogenesis." (PMID 41156009, 2025). "In addition, the expression of MIAT correlated with the MED12 mutation status of the leiomyomas, and knock down of MIAT in leiomyoma smooth muscle cells’ spheroids blocked the effects of TGF-β3 on the induction of COL1A1 and COL3A1 expression." (PMID 38279317, 2024). "Leiomyomas with a MED12 mutation are smaller in size and are frequently located subserously." (PMID 38279317, 2024). "How the missense mutations to MED12 reported in leiomyoma affect PRICKLE1 and the WNT/PCP pathway, in addition to REST localization and function are currently unknown." (PMID 39314474, 2024). "Over 70% of leiomyoma (LM) harbor MED12 mutations, primarily in exon 2 at c.130-131 (GG)." (PMID 39273004, 2024). "Additionally, the expression level of the lncRNA SRA1 has been observed to correlate with the MED12 mutation status in leiomyomas." (PMID 39519092, 2024). "Using next-generation RNA sequencing, we developed a comprehensive profile of differentially expressed sncRNAs and lncRNAs in leiomyomas, demonstrating the impact of race/ethnicity and MED12 mutation on their expression and highlighting their significance in leiomyoma pathogenesis." (PMID 39519092, 2024). "Additionally, MED12 mutations are associated with greater number of individual fibroids, subserousal fibroids, and are more common in black women compared to white and Asian women." (PMID 38957794, 2024). "Recurrent somatic MED12 mutations drive fibroid tumors in 70% of cases." (PMID 37429859, 2023). "Of the 73 paired specimens, 48 leiomyomas had MED12 mutations (65.8%)." (PMID 36835153, 2023). "This analysis indicated that the expression of WNT16, CACNA1D, DCX, and WIF1 was significantly higher, while the expression of MTMR8 was significantly lower in myometrium adjacent to MED12-mutated leiomyomas compared to myometrium adjacent to MED12 wild-type leiomyomas." (PMID 36835153, 2023). "The impact of the high occurrence of MED12 mutations in leiomyomas on the expression of genes critical to leiomyoma pathogenesis remains unknown." (PMID 36835153, 2023). "Unlike HMGA2 rearrangements, HMGA1 and PLAG1 rearrangements are rare in leiomyomas and may co‐occur with MED12 mutations, suggesting that they are secondary events related to tumor progression." (PMID 35822448, 2023). "In conclusion, MED12 mutations have profound effects on the expression of genes pivotal to leiomyoma pathogenesis in the tumor and the myometrium which could alter tumor characteristics and growth potential." (PMID 36835153, 2023). "The present study shows that uterine fibroids differ depending on the presence of MED12 mutations." (PMID 35618793, 2022). "Strikingly, approximately 70% of leiomyoma patients possess MED12 mutations in leiomyoma tumors." (PMID 35203298, 2022).
leiomyoma (continued). "Collectively, our results indicate that the differential expression of SE in leiomyomas is another mechanism contributing to dysregulation of protein coding genes in leiomyomas and that race and MED12 mutation can influence the expression of a select group of SE." (PMID 35641855, 2022). "Somatic MED12 mutation in exon 2 occurs at a frequency of up to 80% and has a functional role in leiomyoma initiation and progression potentially through abnormal activation of Wnt/β-catenin signaling, sex steroid receptor signaling, fibrosis-associated gene expression, and cell proliferation." (PMID 35641855, 2022). "The most common driver mutations in leiomyomas are those involving MED12." (PMID 35641855, 2022). "Additionally, our previous studies demonstrated that in cases of multiple myomas, most of the fibroids harbored various MED12 mutations." (PMID 35203716, 2022). "More than 70% of leiomyomas (LM) harbor MED12 mutations, primarily in exon 2 at c.130-131(GG)." (PMID 35869560, 2022). "However, our novel finding that MED12 mutation in LM affects tryptophan metabolism is an important step toward defining the molecular and metabolic signatures of leiomyoma subgroups." (PMID 35064560, 2022). "Altogether, our study demonstrates for the first time, a clear connection between increased myometrial ROS and MED12 mutations that may underlie leiomyoma development." (PMID 35869560, 2022). "Additionally, in primary cell culture of cells obtained from leiomyoma patient tissue samples, a rapid loss of MED12 mutant cells was observed, suggesting a very limited viability of this cell population in culture." (PMID 32094355, 2020). "Therefore, MED12 mutation-driven leiomyoma disease pathogenesis is more likely a result of CDK8 kinase activity defects, and not cyclin C-CDK8 binding defects, and future work will be required to identify the kinase substrate of the CDK8 submodule." (PMID 32094355, 2020). "Fibroid tumors stratify into four main subtypes that are dependent on the mutational status of mediator of transcription subunit 12 (MED12), fumarate hydratase (FH), high mobility group AT-hook 2 (HMGA2) translocations, and collagen (COL4A5-COL4A6) gene deletions." (PMID 32094355, 2020). "The mechanism by which exon 2 mutations in MED12 lead to leiomyomas is not well understood." (PMID 32094355, 2020). "Together, these findings strongly point to a causal role of MED12 in fibroids." (PMID 31089260, 2019). "Like other oncogenes, majority of MED12 mutations are located recurrently at the same amino acid position (codon 44), suggesting that glycine at codon 44 is mutation hotspot for leiomyomas and its location in evolutionarily conserved nucleotide sequences makes it a putative causal variant." (PMID 30619444, 2018). "Nevertheless, some histopathological characteristics of leiomyosarcomas such as mitotically active cells have also appeared in leiomyoma cases with MED12 mutations, indicating possible transformation of leiomyoma toward malignancy when somatic mutations are accumulated." (PMID 30619444, 2018). "Therefore, we sought to replicate the MED12 mutation frequency in leiomyomas of Saudi Arabian women, who represents ethnically and culturally distinct population." (PMID 30619444, 2018). "The multiplicity of MED12-mutation-positive leiomyomas may derive from genetic predisposition and/or environmental factors rendering the myometrium susceptible to selection for MED12 mutations." (PMID 28432313, 2017). "First, to test whether tumour size, location and histotype are associated with the MED12-mutation status of the leiomyomas, we fit a generalised estimating equations (GEE) model." (PMID 28432313, 2017). "Mutations of MED12 were found in leiomyomas with a normal karyotype, with deletions or rearrangements of the long arm of chromosome 7 as sole anomaly, and with 6p21∼23 abnormalities leading to HMGA1 rearrangement/overexpression, and it was concluded that they precede the chromosomal aberrations." (PMID 28591699, 2017).
leiomyoma (continued). "Out of 763 leiomyomas, 599 (79%) harboured a MED12 mutation." (PMID 28432313, 2017). "The molecular pathogenesis of uterine leiomyomas in SC2 may be different from that of leiomyoma with MED12 mutations." (PMID 27498619, 2016). "Also, they tend to occur as solitary nodules whereas often multiple clonally independent leiomyomas with MED12 mutations have been described." (PMID 26468330, 2015). "Whole exome sequencing revealed that the gene encoding transcription factor MED12 (Mediator complex subunit 12) harbored heterozygous missense mutations caused by single nucleotide variants in highly conserved codon 44 of exon 2 in two of five leiomyomas." (PMID 22428002, 2012). "DNA variants in leiomyomas were confined to exon 2 of MED12." (PMID 22428002, 2012). "MED12 mutations were recently described in leiomyomas from a group of Finnish women." (PMID 22428002, 2012). "Somatic MED12 exon 2 mutations were observed in uterine leiomyosarcomas, suggesting that a subgroup of these malignant tumours may develop from a leiomyoma precursor." (PMID 23132392, 2012). "It is now essential to validate our hypotheses regarding the role of MED12 mutations in leiomyoma development and MED12 inhibition in leiomyosarcomas oncogenesis." (PMID 22768200, 2012). "However, given that MED12 mutations disrupt mediator complex activity, altering transcriptional activity in leiomyomas, MED12 interaction with GR signaling, and/or FKBP51 may be interesting to investigate in future studies." (PMID 40290045, 2025). "Therefore, the objective of the present study was to determine and compare the expression profile of differentially expressed coding RNA transcripts using high-throughput sequencing and in-depth data analysis based on the MED12 mutation status of the leiomyoma." (PMID 36835153, 2023). "Hence, it is plausible to hypothesize that the initial MED12 mutation occurs in these stem and progenitor cells, which subsequently interact with the surrounding myometrial tissue to give rise to a fibroid tumor." (PMID 37429859, 2023). "Indeed, 80–90% of leiomyomas harbor one of three genetic changes: a hotspot mutation in mediator complex subunit 12 (MED12), a chromosomal aberration resulting in upregulation of high mobility group AT-hook 2 (HMGA2), or biallelic loss of fumarate hydratase (FH)." (PMID 36068196, 2022). "Leiomyomas expressing mutated mediator complex subunit 12 (mut-MED12) were reported to contain significantly decreased tryptophan levels; the underlying mechanism and the role of the tryptophan metabolism-kynurenine pathway in leiomyoma tumorigenesis, however, remain unknown." (PMID 35064560, 2022). "Indeed, 80−90% of leiomyomas harbor one of three genetic changes: a hotspot mutation in mediator complex subunit 12 (MED12), a chromosomal aberration resulting in significant overexpression of high mobility group AT-hook 2 (HMGA2), or biallelic loss of fumarate hydratase (FH)." (PMID 33352722, 2020). "There is an inverse correlation between presence ofMED12 mutation and leiomyoma size, suggesting that lesions of differing sizes may have different aetiological pathways.MED12 mutations seem relatively specific for leiomyoma, and also occur in around 10 – 20% of leiomyosarcomas." (PMID 29259779, 2017). "MED12 wild-type (WT) leiomyomas are larger and more often found as solitary nodules compared to MED12 mutant (MUT) leiomyomas." (PMID 41493967, 2026). "Somatic mutations in exon 2 of the gene encoding mediator complex subunit 12 (MED12) are most common, found in approximately 70% of leiomyomas." (PMID 41493967, 2026). "We, therefore, explored CDK8 as a therapeutic target and investigated its activity in leiomyoma in relation to MED12 status and sex steroid hormone kinetics using clinical samples." (PMID 41493967, 2026). "Cell proliferation and apoptosis of primary cultured MED12 wild-type leiomyoma cells were evaluated in the presence of a CDK8 inhibitor and sex steroid hormones." (PMID 41493967, 2026).
leiomyoma (continued). "Although MED12 exon 2 mutations and CDK8 activity have been reported in leiomyoma cells and tissues, this is the first report clarifying their association with patient treatment history." (PMID 41493967, 2026). "CDK8 was co-immunoprecipitated from leiomyoma tissue extracts using MED12 antibody to test its kinase activity in vitro, and the amount of phosphorylated substrate was measured." (PMID 41493967, 2026). "Active leiomyoma cell proliferation has been observed in MED12 WT leiomyomas, whereas an increase in the extracellular matrix (ECM) is prominent in MED12 MUT leiomyomas." (PMID 41493967, 2026). "Our results reinforced previous findings by showing significantly reduced CDK8 kinase activity towards RNAPII CTD in MED12 MUT leiomyomas." (PMID 41493967, 2026). "In uterine leiomyoma cell lines, MED12 knockdown significantly reduces the expression levels of ERα and PR and decreases the proliferation of human leiomyoma cells mediated by the Wnt/β-catenin signaling pathway." (PMID 40940746, 2025). "Specific MED12 peaks in leiomyoma samples are enriched in H3K27ac-marked leiomyoma-specific genomic regions and show less enrichment in normal myometrium." (PMID 40345582, 2025). "When comparing endometrial samples from patients with MED12-mutant fibroids (n = 10) and those with wild-type MED12 (n = 5), 2,784 transcripts across 2134 genes (p-value < 0.05 and OFDR < 0.05) were identified." (PMID 40739398, 2025). "Leiomyomas are also characterized by activation of the WNT/β-catenin pathway, which is correlated with MED12 mutation status." (PMID 38279317, 2024). "Our data indicate that the expression of a number of genes regulating calcium homeostasis is dysregulated in leiomyomas in a MED12-dependent manner." (PMID 36835153, 2023). "The accuracy of diagnosis is facilitated by the absence or extremely low level of HMGA2 expression in normal myometrium, although there are reports of the possibility of moderate HMGA2 expression in MED12-dependent fibroids." (PMID 37987267, 2023). "Driver mutations in the transcriptional mediator complex subunit 12 (MED12) gene in uterine myometrial cells initiate 70% of leiomyomas that grow in a progesterone-dependent manner." (PMID 37607000, 2023). "The samples were analyzed together with a previously published dataset of 44 leiomyomas with a driver alteration in MED12, HMGA2, or FH as well as five myometrium samples." (PMID 35822448, 2023). "Integration of cistromic and transcriptomics data identified tryptophan 2,3-dioxygenase (TDO2) as the top mut-MED12 target gene that was significantly upregulated in mut-MED12 leiomyomas when compared with adjacent myometrium and WT-MED12 leiomyomas." (PMID 37607000, 2023). "The MED12 mutant Fibroid tumors are known to have higher abnormal progression of the replication fork and increased R-loop formation." (PMID 37429859, 2023). "We performed an immunohistochemistry analysis of γH2AX on a well-annotated tissue microarray containing normal myometrium and MED12 mutant fibroid tumors (n = 10)." (PMID 37429859, 2023). "Trials of these inhibitors should be carried out mainly on patients with MED12-dependent leiomyomas." (PMID 37987267, 2023). "MED12, implicated as an oncogene in about 70% of uterine leiomyoma, is a target of hsa-miR-10a-5p, whose expression is gradually reduced from AF-MSCS to L-MSCs, possibly explaining the upregulation of MED12 in leiomyoma." (PMID 35885889, 2022). "Strikingly, we determined that myometrial and MED12 mutant leiomyoma cells repopulated cell-depleted tissue slices after 20 days of culture." (PMID 35884847, 2022). "The driver mutations critical to leiomyoma development and progression include MED12 (mediator complex subunit 12), HMGA2 (high mobility group AT-hook 2), FH (fumarate hydratase), and COL4A5/6 (collagen type IV, alpha 5, and alpha 6)." (PMID 35641855, 2022).
leiomyoma (continued). "The HMGA2 (high mobility group AT-hook 2) gene is overexpressed in 65% of these types of tumors and mutations in a transcriptional regulator complex subunit 12 (MED12) are demonstrated in 70% of fibroids." (PMID 34442017, 2021). "All leiomyomas showed dysregulation of 70 metabolites, and distinct metabolomics profiles were seen for different genetic subtypes of leiomyomas (i.e.; FH, MED12, HMGA2)." (PMID 33371433, 2020). "This suggests that the changes in gene expression between normal and MED12 mutant disease tissue types are primarily attributable to biological pathways that are important for the development and maintenance of the leiomyoma disease state." (PMID 32094355, 2020). "For example, leiomyomas of the MED12 subtype are typically more numerous, smaller in size, and subserosal; leiomyomas of the HMGA2 subtype are larger, isolated, and have a high vasculature density making them potentially sensitive to angiogenesis inhibitors." (PMID 33352722, 2020). "Using high-resolution ChIP-sequencing, promoter capture Hi-C, and RNA-sequencing of matched normal and leiomyoma tissues, here we show that modified enhancer architecture is a major driver of transcriptional dysregulation in MED12 mutant uterine leiomyomas." (PMID 32094355, 2020). "HMGA2 translocations were described in 45% of tumors not containing MED12 mutations, suggesting multiple, less prevalent, genetic aberrations are responsible for the remaining 55% of non-MED12 altered leiomyomas." (PMID 31027501, 2019). "In this report we show that H19 expression is significantly increased in fibroids as compared with normal myometrium, and that H19 functions to promote leiomyoma cell proliferation and expression of MED12, HMGA2, TET3, and ECM-remodeling genes." (PMID 31089260, 2019). "The most common subtype is MED12 mutant leiomyoma (MED12-LM), which accounts for approximately 70% of all UL cases." (PMID 30547045, 2018). "Noticeably, in 3/30 (10%) mutation positive cases, nucleotide changes were large indels, which further underscores the frequent genetic instability of MED12 gene in leiomyomas." (PMID 30619444, 2018). "Three uterine smooth muscle tumors (two conventional leiomyomas and one leiomyosarcoma) harbor large MED12 exon 2 deletions (PDF 175 kb)." (PMID 28592321, 2017). "Prolactin was one of the most up-regulated genes in leiomyomas with HMGA2 rearrangements, MED12 mutations and COL4A5-COL4A6 deletion supporting its role as a mitogenic autocrine growth factor in human leiomyoma tumorigenesis." (PMID 28930160, 2017). "Here we describe a patient who underwent hysterectomy because of multiple leiomyomas which were studied by cytogenetics, MED12 hotspot sequencing, and copy number variation arrays." (PMID 26468330, 2015). "We directly sequenced the MED12 gene in 3 pairs of normal myometrium and adjacent leiomyoma tissues, as well as in main population and SP cells isolated from these samples." (PMID 22570742, 2012). "We then sequenced MED12 in an additional 143 leiomyomas and 73 normal myometrial samples; the leiomyomas were all derived from different individuals and the corresponding myometrial samples were taken from 73 of those individuals." (PMID 22428002, 2012). "Although the mechanism by which decreased CDK8 activity suppresses leiomyoma growth remains unclear, this study revealed a GnRH agonist-induced reduction in MED12-dependent CDK8 activity." (PMID 41493967, 2026). "Previous studies have shown that PR signaling is particularly activated in MED12 MUT leiomyomas and CDK8 inhibition may influence PR expression or activity in MED12 WT leiomyomas." (PMID 41493967, 2026). "Indeed, pathogenic exon 2 mutations in MED12 have been shown to reduce CDK8/19 kinase activity both in vitro and in patients with clinically significant leiomyomas." (PMID 41156009, 2025).